APOL1 (apolipoprotein L1)
Diseases named in the same sentence as APOL1 in open-access papers (continued):
Sharing a sentence is not in itself a finding about the gene and the disease.
tumor (continued). "Tumor types differ in their microenvironmental and metabolic characteristics, which may influence APOL1 function." (PMID 41378287, 2025). "The analyses indicated that genes positively correlated with APOL1 expression are potentially involved in regulating immune functions within tumor tissues, whereas negatively correlated genes may influence tumor cell metabolism and proliferation." (PMID 41378287, 2025). "For example, in PTC, APOL1 may act as a tumor suppressor by regulating pathways that inhibit cell proliferation or promote apoptosis." (PMID 41378287, 2025). "Intertumoral heterogeneity may also lead to divergent roles of APOL1 within the same cancer or cell type, further complicating its involvement in tumor progression." (PMID 41378287, 2025). "Recent research revealed that APOL1 contributes to tumor progression." (PMID 40649778, 2025). "APOL1, TNF, and VIM co-expressed in myeloid cells, indicating that PANoptosis–lactylation interplay may counteract APOL1’s tumor-promoting effects by activating caspase cascades." (PMID 40649778, 2025). "Lastly, the function of APOL1 may vary depending on the tumor microenvironment and cell type, as APOL1 interacts with different molecules in different microenvironments, potentially exhibiting diverse functions." (PMID 41378287, 2025). "The low basal expression of APOL1 in tumor cells may already be sufficient to fulfill its oncogenic functions, while the downregulation of APOL1 in tumor cells could be a strategy employed by cancer cells to achieve immune evasion." (PMID 40649778, 2025). "Altogether, these findings show that APOL1’s oncogenic role might be counterbalanced by lactylation–PANoptosis interactions in the tumor microenvironment." (PMID 40649778, 2025). "Moreover, NOP2 overexpression increased tumor size and weight in subcutaneous ccRCC mice; however, these effects were mitigated by APOL1 knockdown." (PMID 39309431, 2024). "To determine whether APOL1 dependent Akt pathway could be involved in cell migration of tumor cells, we checked the Akt pathway in the APOL1 knockdown or overexpressing cells." (PMID 38680858, 2024). "Thus, APOL1 is a critical target of the HIF-2α pathway involved in clear cell tumor progression and lipid storage." (PMID 38263248, 2024). "This was the same as drop APOL1 protein expression in more aggressive tumor grades." (PMID 38680858, 2024). "BIRC3 was detected in 50% of tumours, and APOL1 expression in 64%." (PMID 38254861, 2024). "Silencing APOL1 expression inhibited ccRCC cell proliferation in vitro and tumor formation in vivo." (PMID 39309431, 2024). "In conclusion, our study revealed that APOL1 play a role as a tumor suppressor in ccRCC and inhibit metastasis, which may provide novel potential therapeutic approaches for ccRCC patients." (PMID 38680858, 2024). "APOL1, found as a tumor suppressor in our study, is one of the upregulated downstream genes of HIF." (PMID 38680858, 2024). "Since ccRCC is considered a “metabolic disease” and “VHL hyper-mutation disease”, one unexplored avenue of controlling this tumor is to target the HIF2α/LINC02609/APOL1 pathway, which may offer a veritable therapeutic window." (PMID 38263248, 2024). "We also showed that high APOL1 expression correlated with worse clinical outcomes, and knockdown of APOL1 inhibited tumor cell lipid droplet formation, proliferation, metastasis and xenograft tumor formation abilities." (PMID 38263248, 2024). "In addition, we used a subcutaneous ccRCC mouse model to determine the role of APOL1 in vivo, which indicated that APOL1 silencing markedly suppressed tumor growth in the mice model than in the controls." (PMID 39309431, 2024). "We found that APOL1, 3, and 6 were differentially expressed in tumor and non-tumor tissues." (PMID 38017264, 2023). "APOL1, 3 and 6 were differentially expressed in tumor and non-tumor tissues in the TCGA cohort." (PMID 38017264, 2023).
tumor (continued). "APOL1 protein expression levels were higher in PC compared with those in paired non-tumor tissues." (PMID 34341330, 2021). "Likewise, these in vivo experiment results were consistent with in vitro findings that APOL1 knockdown inhibited tumor growth and induced apoptosis of PC cells." (PMID 34341330, 2021). "Further investigation verified that knockdown of APOL1 observably inhibited cell growth and promoted cell cycle arrest and apoptosis in vitro, and inhibited cell proliferation in vivo, as evidenced by decreased tumor size in the PC mouse model." (PMID 34341330, 2021). "Moreover, APOL1 silencing inhibited PC cell growth and induced cell cycle arrest and apoptosis in vitro, and suppressed tumor growth in vivo." (PMID 34341330, 2021). "Additionally, the role of APOL1 may be time-dependent; it could inhibit cell proliferation during certain stages of tumor development, while playing a more complex role in invasion and metastasis at later stages." (PMID 41378287, 2025). "Furthermore, TGFBI, PLOD2 and APOL1 had clear tumor progression patterns in the TCGA-KIRC dataset." (PMID 38680858, 2024). "In summary, suppression of APOL1 activated tumorigenic pathways, especially that of Akt, in which FAK contributed to increase tumor aggressiveness through the expression of adhesion molecules and EMT processes." (PMID 38680858, 2024). "Recent studies indicated that APOL1 exhibited oncogenic effects in PAAD, inhibiting PAAD cell apoptosis and promoting tumor cell proliferation through activation of the NOTCH1 signaling pathway, which was the first study reporting APOL1 function in PAAD." (PMID 37588985, 2023). "We can find that the expression of GNG7, MXRA7, ASB2, and PDGFD in tumor samples is significantly lower than that in normal samples, while the expression of RPS6KA1, CHMP4C, APOL1, and LYPD3 is reverse." (PMID 36225190, 2022). "The results showed that RPS6KA1, PDGFD, APOL1, and LYPD3 are all upregulated in tumor tissues, which were consistent with GEPIA2." (PMID 36225190, 2022). "Using in vivo tumor generation as the gold standard for tumorigenic potential, we observed that RCC cancer cells which express the APOL1 G1 and G2 RV fail to generate tumors in mice." (PMID 35159001, 2022). "According to the expression and survival analysis, three genes (COL12A1, APOL1, and MMP14) were significantly higher in tumor samples when compared with normal controls and their upregulation indicated a poor prognosis." (PMID 33027767, 2020). "Among them, four genes, including APOL1, CCL17, RBP4, and KRT71 were selected in real-time PCR experiments between tumor samples and normal samples, which were found to be consistent with the expression trend in low- and high-risk groups." (PMID 33335850, 2020). "Western blot analysis from tumor homogenates show that vitexin increased in levels of p-JNK, LC3-II and ApoL1." (PMID 29348836, 2017). "On the other hand, four genes (ANKRD11, PHLDA3, APOL1 and MSX1) are known as tumour-suppressor factors." (PMID 19826427, 2009). "Additionally, we identified APOL1 as a poor prognostic factor in LUAD, highlighting its potential as a marker mediating tumor progression." (PMID 40649778, 2025). "We found that APOL1, 3, and 6 were differentially expressed in tumor and non-tumor tissues in both cohorts." (PMID 38017264, 2023). "As dysfunctional mitochondria have been shown to contribute to tumor progression, we examined whether the metabolism and the bioenergetics are altered in RCC cells that express the APOL1 RV and manifest the swelling morphology." (PMID 35159001, 2022). "In addition to the robust induction of type I and type III interferons, expression of APOA1, APOL1, APOL3, and CH25H was increased from 10 to >50-fold, depending on the cell line (C1 or C2) from which the tumor originated." (PMID 34983824, 2022).
tumor (continued). "Analysis of TCGA datasets demonstrated a close correlation between APOL1 expression and clinical as well as prognostic outcomes in THCA, including variables such as pathologic N stage, overall pathologic stage, age, histologic type, primary neoplasm focus type and neoplasm location." (PMID 41378287, 2025). "Notably, TRIM31 (logFC = 1.14), ANXA1 (logFC = 1.05), GBP1 (logFC = 1.01), BIRC3 (logFC = 0.99), APOL1 (logFC = 0.97), IL18 (logFC = 0.94), ANXA2 (logFC = 0.89), BHLHE40 (logFC = 0.83), and EPHA2 (logFC = 0.75) exhibited significant upregulation in tumour tissues." (PMID 38254861, 2024).
cancer (24 papers, 2009 to 2025). A tumor composed of atypical neoplastic, often pleomorphic cells that invade other tissues. "We focused on the novelty of APOL1 as a potential cancer marker whose low expression strongly associated to poor survival rate at metastatic stage of ccRCC, considering that TGFBI had already been identified as oncogene in RCC." (PMID 38680858, 2024). "Changes in APOL1 function caused by various factors can lead to lipid disorders, cancer and other diseases." (PMID 38410113, 2024). "Autophagy, which was also proposed as a mechanism responsible for APOL1 RV cytotoxicity, is associated with increasing levels of APOL1 expression in normal and cancer cells." (PMID 35159001, 2022). "Since RCC are high energy demanding cancer cells, as indicated by their proliferation rates in vitro and in vivo, it was important to examine the mitochondrial function of APOL1 variants by an analysis that directly measures mitochondrial respiration." (PMID 35159001, 2022). "In the present study, analysis of TCGA data revealed high APOL1 expression in 14 cancer types, notably in THCA, where it was significantly upregulated compared to normal tissue." (PMID 41378287, 2025). "In the Human Protein Atlas database, APOL1 notably has the highest RNA expression level in many kidney cancer cell lines compared to other cancer types." (PMID 38680858, 2024). "To further study the role of APOL1, we examined its clinical relevance in cancer patients at the protein level." (PMID 38263248, 2024). "In our study, the mRNA expression of APOL1 is increased according to the stages of cancer, however, the protein level is dropped at the later stages." (PMID 38680858, 2024). "Taken together, we found that APOL1 was critical in the progression of ccRCC, but was shown to block metastasis at later stages of cancer." (PMID 38680858, 2024). "Altogether, these results suggest that the complicated lipid and cholesterol homeostasis in cancer cells, tightly regulated through APOL1, LCAT, and ApoA-I, deserve a deeper mechanistic investigation." (PMID 36672361, 2023). "Overall, our results suggest that APOL1 plays a role in inhibiting autophagy in RCC cancer cells, and that this function is disrupted upon knock-out of APOL1 expression or due to expression of the APOL1 G1 and G2 RV." (PMID 35159001, 2022). "APOL1 belongs to the APOL gene family and acts as a minor component of HDL, and this gene family is associated with various cancers." (PMID 34341330, 2021). "Given the biological function of APOL1 in autophagy and cell death, its potential role in regulating cancer growth and outcomes seems more evident." (PMID 34733899, 2021). "The KEGG analysis also showed that the depletion of APOL1 is related to transcriptional misregulation in cancers, which means that it may have a significant impact on the development of tumors." (PMID 38263248, 2024). "This phenomenon infers that APOL1 may be modulated during its transcriptional or translational processes to be reduced in its expression in later cancer stages." (PMID 38680858, 2024). "Similarly, transcriptome sequencing analysis of ccRCC against adjacent normal tissues in our research demonstrated that APOL1 was highly expressed in the cancer samples with high mortality rates." (PMID 38680858, 2024). "Additionally, the prevalence of m5C modification of APOL1 in different types of cancer cells requires further validation." (PMID 39309431, 2024). "Furthermore, adenosine to inosine RNA editing events is notably found in the 3’UTR region of APOL1 across 33 cancer types from TCGA dataset." (PMID 38680858, 2024). "APOL1 therefore is involved in diverse cellular processes and may have different roles depending on cancer types." (PMID 38680858, 2024).
cancer (continued). "This raised the question of how these cancer cells tolerate high APOL1 levels, and whether they could tolerate high levels of the APOL1 G1 and G2 RV, as well." (PMID 35159001, 2022). "Our findings suggest that, in contrast to the WT APOL1 variant, APOL1 RV are toxic for RCC cells and may act to suppress cancer cell growth." (PMID 35159001, 2022). "RCC cancer cells can hardly tolerate increased APOL1 risk variants expression levels as opposed to APOL1 G0." (PMID 35159001, 2022). "This analysis supports the notion that the genetic manipulation of APOL1 in RCC cancer cells leads to an alteration in mitochondrial metabolism, which in turn influences downstream gene expression, signal transduction, and the tumorigenic capacity of the cells." (PMID 35159001, 2022). "In previous reports, APOL1 was considered to be highly elevated in various cancers, including PC." (PMID 34341330, 2021). "Further investigations into the role of APOL1 in both cancer and CVD are certainly warranted." (PMID 34733899, 2021). "APOL1 is a novel BH3-only protein, and its overexpression could induce autophagy and autophagy-associated cell death in several types of cancer cells." (PMID 33587010, 2021). "However, little research has been conducted on the regulation of APOL1 expression in cancer." (PMID 38263248, 2024). "Nevertheless, the function or mechanisms of APOL1 in cancer remain unclear." (PMID 38263248, 2024). "Additionally, understanding how APOL1 cytotoxicity is abolished in RCC cancer cells could potentially shed light on the mechanism/s by which high levels of APOL1 induce toxicity in normal cells." (PMID 35159001, 2022). "Hence, we examined whether APOL1 gene editing in these cancer cells affects their tumorigenic capacity in vivo." (PMID 35159001, 2022). "Expression validation in the transcriptome, TCGA–BLCA, and GSE13507 datasets confirmed the up-regulation of APOL1, DHX34, and TNK2, and the down-regulation of AHNAK, CSPG4, NCAM1, and PCDHB4 in the cancer group." (PMID 40908816, 2025). "The results showed that APOL1 was upregulated in cancer tissues compared with adjacent normal tissues." (PMID 41378287, 2025). "We demonstrate that the substitution of one nucleotide for expressing the APOL1 G1 or deletion of six nucleotides for expressing the APOL1 G2 led to a significant alteration in cell metabolism and tumorigenic potential in RCC cancer cells, as did deleting the endogenous gene." (PMID 35159001, 2022). "However, considering the characteristics of SP cells for cancer-initiating ability, the apoptosis-related molecules among these genes (MCL-1, ANKRD11, PHLDA3 and APOL1) might have roles in the proliferation of SP cells." (PMID 19826427, 2009). "Together, these results suggest that parental RCC cancer cells, expressing the APOL1 G0 variant, respond better to environmental changes by adjusting their energy production through mitochondrial respiration, as opposed to RCC cells expressing APOL1 RV or RCC APOL1 null cells." (PMID 35159001, 2022).
cardiovascular disease (20 papers, 2015 to 2025). "Polymorphisms in the Apolipoprotein L1 (APOL1) gene are common in ancestrally African populations, and associate with kidney injury and cardiovascular disease." (PMID 36238153, 2022). "In clinical studies, data on associations of the APOL1 renal risk variants with cardiovascular disease have been complex, with evidence for increased risk and also with decreased carotid artery calcified plaque and improved survival." (PMID 30998685, 2019). "Carriage of two APOL1 risk variants may also be associated with increased risk for cardiovascular diseases (CVDs)." (PMID 40459058, 2025). "Carriage of two APOL1 risk variants may also be associated with increased risk for cardiovascular diseases (CVD)." (PMID 39803526, 2024). "Whether APOL1 high-risk variants are independent risk factors for cardiovascular diseases is unclear and requires further investigation." (PMID 39803526, 2024). "APOL1 is a risk factor for kidney and cardiovascular diseases." (PMID 36225190, 2022). "Additionally, APOL1 has been associated with an increased burden of cardiovascular disease in African Americans participating in the Jackson Heart Study." (PMID 26147622, 2015). "To investigate the effect of APOL1 genotype in cardiovascular diseases, we established and characterized a mouse model, by crossing ApoE knock-out mice and BAC/APOL1 mice carrying the APOL1-G0 or APOL1-G1 variant controlled by the human APOL1 gene locus promotor." (PMID 39803526, 2024). "More recently, a variety of studies have evaluated the role of APOL1 in cardiovascular disease." (PMID 31532792, 2019). "It is unknown if similar age-dependent relationship pattern could also be seen in cardiovascular disease–APOL1 interaction." (PMID 27900314, 2016).
infectious disease (9 papers, 2012 to 2025). A disorder directly resulting from the presence and activity of a microbial, viral, or parasitic agent in humans. "Brazil is a conducive site for studies on CG because of its significant burden of infectious diseases and a high frequency of APOL1 risk variants." (PMID 41397399, 2025). "Thus, the Brazilian population shows considerable potential for the study of CG, owing to the high incidence of infectious diseases and risk populations with an elevated prevalence of the APOL1 high‐risk genotype." (PMID 41397399, 2025). "Flex-sweep also identified sweep windows in TLR5 (Toll-like receptor 5), ITGAE (integrin subunit alpha E), and APOL1 (apolipoprotein L1), all previously identified as sweeps associated with infectious diseases or pathogen response by both genomic and functional studies." (PMID 37307561, 2023). "Unfortunately, our study lacked data on medicinal and herbal treatments, APOL1 genetic variations, as well as on infectious diseases, valuable insights given the relevance of these factors within Africa, beyond metabolic risks." (PMID 39837584, 2025). "Indeed, beyond its proven capacity for trypanolysis, APOL1 was shown to limit Leishmania major infections in mice and suppress HIV-replication in macrophages, hinting at a much broader role for APOL1 in innate immunity to infectious disease." (PMID 28537557, 2017).
bacterial infections (3 papers, 2021 to 2024). "Donor’s APOL-1 high-risk variants have been proposed to increase the risk of de novo collapsing FSGS, particularly in recipients with additional injury induced by viruses or bacterial infections." (PMID 39866980, 2024).
immune disease (2 papers, 2018 to 2022). "Clinical associations between the APOL1 high risk genotype (HRG) and disease are stronger in those with comorbid infectious or immune disease." (PMID 36238153, 2022).
psychiatric disorder (1 paper, 2022). A disorder characterized by behavioral and/or psychological abnormalities, often accompanied by physical symptoms. "Recent studies found that APOL1 was involved in brain structure and psychiatric disorders." (PMID 35870967, 2022).